CNTN5 (contactin 5)
Description:
Contactins mediate cell surface interactions during nervous system development. Has some neurite outgrowth-promoting activity in the cerebral cortical neurons but not in hippocampal neurons. Probably involved in neuronal activity in the auditory system (By similarity).
Synonyms: hNB-2; NB-2; HNB-2s
Tractability: Antibody: its Gene Ontology location is reachable by antibodies, with high confidence; UniProt places it where antibodies can reach, with medium confidence; UniProt predicts a signal peptide or a membrane-spanning region. PROTAC: its protein half-life has been measured.
Gene: Protein-coding gene on chromosome 11 (99,020,949 to 100,358,885, forward strand). Ensembl gene ENSG00000149972.
Subcellular location: Cell membrane
Pathways (Reactome):
Metabolism of proteins: Post-translational modification: synthesis of GPI-anchored proteins
Gene Ontology:
Molecular function: cell-cell adhesion mediator activity
Biological process: axon guidance; brain development; cell-cell adhesion; presynapse assembly
Cellular component: axon; extracellular region; plasma membrane; GABA-ergic synapse; presynaptic membrane
Genetic constraint (gnomAD): Loss-of-function variants: 63 observed, 106.44 expected, observed/expected ratio (o/e) 0.59, 90% interval 0.48 to 0.73. The upper end of that interval is the gene's LOEUF score, 0.73, which puts it in group 2 of 6, group 1 being the genes least tolerant of losing a copy. Missense variants: 1,278 observed, 1,201.6 expected, observed/expected ratio (o/e) 1.06, 90% interval 1.01 to 1.11. Synonymous variants: 442 observed, 429.45 expected, observed/expected ratio (o/e) 1.03, 90% interval 0.95 to 1.11.
Homologues: Orthologues: macaque CNTN5 (99% identical), pig CNTN5 (96% identical), rabbit CNTN5 (95% identical), dog CNTN5 (95% identical), guinea pig CNTN5 (94% identical), rat Cntn5 (91% identical), mouse Cntn5 (90% identical), chimpanzee CNTN5 (90% identical), tropical clawed frog cntn5 (78% identical), zebrafish cntn5 (63% identical). Paralogues in human: CNTN4 (51% identical), CNTN3 (51% identical), CNTN6 (47% identical), CNTN1 (41% identical), CNTN2 (41% identical), NRCAM (27% identical), L1CAM (26% identical), CHL1 (25% identical), NFASC (25% identical), ROBO1 (21% identical), NEO1 (21% identical), ROBO2 (20% identical), and 24 more.
Diseases named in the same sentence as CNTN5 in open-access papers:
CNTN5 is named in the same sentence as 44 diseases in open-access papers, as found by Europe PMC text mining. Sharing a sentence is not in itself a finding about the gene and the disease. The quoted sentences say what the papers report.
autism (7 papers, 2011 to 2024). Persistent deficits in social interaction and communication and interaction as well as a markedly restricted repertoire of activity and interest as well as repetitive patterns of behavior. "In parallel with decreased striatal dopaminergic neurite density, LRRK2 G2019S neurons show increased autism-linked CNTN5 adhesion protein expression; glial cells show significant loss of ferritin heavy chain." (PMID 38293195, 2024). "MEAs have been deployed to investigate gene mutations associated with monogenic forms of autism in hiPSC-neurons such as CNTN5, EHMT2, KCNQ2, ATRX, and SCN2A." (PMID 37441676, 2023). "The deletion at 11q22.1 affected the CNTN5 gene and the deletion at 16p11.2 has been reported to be associated with SZ and autism." (PMID 23285208, 2012). "This deletion affects the CNTN5 gene (encoding contactin 5 protein) that plays a role in the formation of axon connections in the developing nervous system and has been suggested to be involved in autism and schizophrenia." (PMID 23285208, 2012). "A recent publication has shown that ASD neurons derived from autism CNTN5+/− or EHMT2+/− human iPSCs develop hyperactive neuronal networks." (PMID 31893021, 2019). "A loss of CNTN5 co-segregated with autism in one family, and one de novo CNV and one non-cosegregating inherited CNV in CNTN6 were found in a Utrecht cohort." (PMID 24756565, 2014). "Currently, CNTN4, CNTN5, and CNTN6 are suggested as potential disease genes for autism." (PMID 24756565, 2014).
autism spectrum disorder (7 papers, 2014 to 2022). A spectrum of developmental disorders that includes autism, and Asperger syndrome. "Likewise, a recent study that investigated Ngn2-induced neuronal network behavior of 12 autism spectrum disorder patients revealed hyperactive neuronal networks specifically from a patient with CNTN5 and a CRISPR-Cas9-engineered line with an EHMT2 mutation." (PMID 34329594, 2021). "One example is the human gained TAD boundary around CNTN5, a gene involved in neuron circuit formation and autism spectrum disorders; this boundary contains AluY elements and is correlated with an increased CNTN5 expression in human compared with macaque." (PMID 35628657, 2022). "Copy number changes of close family members CNTN4, CNTN5, and CNTN6 have been associated with autism spectrum disorders." (PMID 28126037, 2017). "Mutations of CNTN5 and CNTN6 have previously been reported in individuals with autism spectrum disorders (ASDs), but very little is known on their prevalence and clinical impact." (PMID 27166760, 2017). "The CNTN5 gene, coding for contactins which mediate cell surface interactions in the development of the nervous system, is described as been involved in autism spectrum disorders." (PMID 24742288, 2014). "For example, the human-gained TAD boundary around contactin 5 (CNTN5), a gene involved in neuron circuit formation and autism spectrum disorders, contains Alu Y elements and is correlated with increased CNTN5 expression in humans compared to macaques." (PMID 33922141, 2021).
gout (4 papers, 2019 to 2024). A condition characterized by painful swelling of the joints, which is caused by deposition of urate crystals. "If common genetic variation did not contribute to the epigenetic associations of PGGT1B, INSIG1, ANGPTL2, JNK1, and CNTN5 with gout, it would be interesting to clarify mechanisms underlying the differential methylation of these CpG sites in gout." (PMID 32630231, 2020). "We have also discovered that rs7927466 of CNTN5 is a gout susceptibility locus." (PMID 31289104, 2019). "Another GWAS study showed that three loci (CNTN5, MIR302F and ZNF724) were related to the mechanism of gout development, which is different from the gout risk loci that raise serum uric acid levels we know now." (PMID 35909538, 2022). "In conclusion, this study provided evidence of aberrant methylation changes of PGGT1B, INSIG1, ANGPTL2, JNK1, UBAP1, RAPTOR, and CNTN5 in gout." (PMID 32630231, 2020). "In gout patients, seven aberrant DNA methylation sites that were mapped to seven genes (PGGT1B, INSIG1, ANGPTL2, JNK1, UBAP1, RAPTOR, and CNTN5) and survived genetic and meQTL analyses or causal inference tests were discovered." (PMID 32630231, 2020). "This new approach enabled us to identify two novel gout loci (rs7927466 of CNTN5 and rs9952962 of MIR302F) and one suggestive locus (rs12980365 of ZNF724) at the genome-wide significance level (p<5.0×10–8)." (PMID 31289104, 2019). "Given the roles of PGGT1B, INSIG1, ANGPTL2, JNK1, UBAP1, RAPTOR, and CNTN5 in regulating IL-1β or gouty inflammation and differential methylation of these genes in gout, the next important topic is the consequence of manipulating the respective signaling pathways." (PMID 32630231, 2020). "Moreover, measuring transcription factors identified in this study and chromatin immunoprecipitation (ChIP) for these transcription factors would provide more clues about the mechanistic link between PGGT1B, INSIG1, ANGPTL2, JNK1, UBAP1, RAPTOR, and CNTN5 methylation and gout." (PMID 32630231, 2020). "In addition, three genes (CNTN5, MIR302F, and ZNF724) were detected as ‘gout vs. asymptomatic hyperuricemia’-specific genetic factors." (PMID 38397902, 2024). "Taken together, these results suggested that relationships between PGGT1B, INSIG1, ANGPTL2, JNK1, UBAP1, RAPTOR, and CNTN5 methylation and gout were not confounded by genetic mediators." (PMID 32630231, 2020).
Alzheimer disease (2 papers, 2011 to 2021). A progressive, neurodegenerative disease characterized by loss of function and death of nerve cells in several areas of the brain leading to loss of cognitive function such as memory and language. "A second Alzheimer’s disease exosome study incorporated CNTN5 into a panel that predicts Alzheimer’s, with a high AUC44." (PMID 33441605, 2021).
atrial fibrillation (2 papers, 2010 to 2021). A disorder characterized by an electrocardiographic finding of a supraventricular arrhythmia characterized by the replacement of consistent P waves by rapid oscillations or fibrillatory waves that vary in size, shape and timing and are accompanied by an irregular ventricular response. "SNP variants in CNTN5 have been reported to be associated with atrial fibrillation and heart failure." (PMID 20871662, 2010).
attention deficit-hyperactivity disorder (2 papers, 2017 to 2020). A disorder characterized by a marked pattern of inattention and/or hyperactivity-impulsivity that is inconsistent with developmental level and clearly interferes with functioning in at least two settings (e.g. at home and at school). "In family AUDIJ002, a girl with ASD and attention-deficit/hyperactivity disorder carried five copies of CNTN5 transmitted by her mother, who had specific learning disorder (reading)." (PMID 27166760, 2017).
dementia (2 papers, 2025). Loss of intellectual abilities interfering with an individual's social and occupational functions. "Our findings also covered well-known dementia-associated proteins, such as BCAN, CNTN5, and NCAN, along with identifying recently promising biomarkers, including IL18, MMP12, TNFSF12, and UNC5C, where these biomarkers presented the highest protein importance in their clusters." (PMID 40748327, 2025). "Despite most of these being more prominently dysregulated in AD (e.g., SDC4, ITGB2, MIF, and sTREM1), a small subset of proteins showed an opposite effect between these dementias (e.g., CHL1, GPC1, and CNTN5)." (PMID 40866991, 2025).
depression (2 papers, 2018 to 2020). "Of these, CNTN5 in chr11q2 showed evidence for nominal association with number of episodes of depression (SCID), psychological distress (GHQ-28B) and the cognitive variables: digit symbol coding and Mill Hill vocabulary." (PMID 29880880, 2018).
diabetes (2 papers, 2011 to 2021). "A final multivariable model found three proteins (Contactin-5 [CNTN5], Low affinity immunoglobulin gamma Fc region receptor II-a [FCGR2A], and Complement factor B [CFB]) associated with incident CVD after adjustment for diabetes (AUC = 0.82)." (PMID 33441605, 2021).
mental disorder (2 papers, 2018 to 2020). A disease that has its basis in the disruption of mental process. "Although not segregating closely with BD, we identified CNVs affecting intronic regions of candidate genes previously implicated in psychiatric disorders (i.e., NLGN1, CNTNAP2, KCNB2 and CNTN5), each in different families." (PMID 29531218, 2018).
myeloma (2 papers, 2023 to 2025). "Although glutaminyl-peptide cylotransferase (QPCT) and contactin 5 (CNTN5) are not currently known to have any clear function related to B-cell biology or myeloma development, both have been noted to be upregulated in the plasma cells of some patients with myeloma at the single-cell level." (PMID 40334107, 2025).
Parkinson disease (2 papers, 2011 to 2023). A progressive degenerative disorder of the central nervous system characterized by loss of dopamine producing neurons in the substantia nigra and the presence of Lewy bodies in the substantia nigra and locus coeruleus. "According to the PheWeb database, the rs140703637 SNP of the CNTN5 gene is significantly associated with Parkinson’s disease, in which the dopamine system is known to be involved in its etiology; it is also known to be involved in the etiology of PONV." (PMID 37835423, 2023).
cholangiocarcinoma (1 paper, 2021). A carcinoma that arises from the intrahepatic biliary tree (intrahepatic cholangiocarcinoma) or from the junction, or adjacent to the junction, of the right and left hepatic ducts (hilar cholangiocarcinoma). "The top-ranked somatic eQTL genes with missense mutations include USP29 in cholangiocarcinoma (CHOL) and AMELX, CNTN5, and OR1L3 in lymphoid neoplasm diffuse large B-cell lymphoma (DLBC)." (PMID 33691015, 2021).
Crohn disease (1 paper, 2024). A gastrointestinal disorder characterized by chronic inflammation involving all layers of the intestinal wall, noncaseating granulomas affecting the intestinal wall and regional lymph nodes, and transmural fibrosis. "In the study of long-term response and non-response to IFX therapy, rs1813443, located in the intronic section of gene CNTN5, has been associated with clinical and biochemical responses to IFX in Greek patients with Crohn’s disease." (PMID 38612528, 2024).
diabetic retinopathy (1 paper, 2010). "CNTN5 (contactin 5) at 11q22 is also among the nominally associated genes for severe diabetic retinopathy." (PMID 20871662, 2010).
liver cancer (1 paper, 2023). An epithelial or non-epithelial malignant neoplasm that arises from the liver. "Moreover, the mutations in CNTN5 were reported to contribute to the metastatic process of pancreatic cancer, HTR4 was found predominantly in only high-grade prostate cancer, and the high expression of TEKT3 could be influenced by HBV integration events in liver cancer." (PMID 36816541, 2023).
lymphoid cancer (1 paper, 2022). "To address the question whether RAG nicking could occur at regions which are not known to undergo rearrangements in lymphoid cancer patients, but possesses CpG and cryptic nonamers, we selected 3 random regions (ERP44, CNTN5 and an unannotated region) of the human genome." (PMID 36228010, 2022).
RASopathy (1 paper, 2017). Developmental syndromes caused by germline mutations (or in rare cases by somatic mosaicism) in genes that alter the Ras subfamily and mitogen-activated protein kinases that control signal transduction. "Additional genes listed in SFARIgene adjacent to our top RASopathy social responsiveness QTL results include CNTN5, ESRRB, GABRB1, GNB1L, and ICA1." (PMID 28076348, 2017).
Sepsis (1 paper, 2022). Sepsis is defined as life-threatening organ dysfunction caused by a dysregulated host response to infection. "CNTN5, a member of the immunoglobulin superfamily, is a glycosylphosphatidylinositol-anchored membrane protein known to mediate nervous system development, which is relatively unexplored in sepsis." (PMID 36572854, 2022). "Of the ICU Day-3 classifying proteins, ST2, CNTN5, and ITGAV decreased significantly in median level from ICU Day-1 to Day-3 and VSIG4 increased significantly in sepsis patient plasma between Day-1 and Day-3." (PMID 36572854, 2022).
thyroid cancer (1 paper, 2024). "Using 20 thyroid cancer and 7 control cancer cell lines, we discovered that variants rs200077102 within FN1 and rs78588384 within CNTN5 displayed comparable low MAF in vitro as observed in the PTC blood and tumor samples." (PMID 39770638, 2024). "Sanger sequencing analyses of 20 thyroid and 5 non-thyroid cancer cell lines confirmed associations with PTC, particularly for MSTA HERV-L variant rs200077102 within the FN1 gene and HERV-L MLT1A LTR variant rs78588384 within the CNTN5 gene." (PMID 39770638, 2024).
cancer (10 papers, 2015 to 2024). A tumor composed of atypical neoplastic, often pleomorphic cells that invade other tissues. "Genes potentially associated with cell migration and cancer metastasis included CNTN5, FN1, Integrin Subunit Beta 6 (ITGB6), EPHB1, Unc-5 Netrin Receptor D (UNC5D), SDK1, RADIL, LRRC7, PCDH11X, and ADAMTS9." (PMID 39770638, 2024). "Among all 169 potential cancer drivers, 33 genes, including Notch1, Jup and Met, showed oncogenic features, whereas the majority of genes, including Lipc, Cntn5, Hdac4, Nrxn3 and Cntnap5c, exhibited tumour suppressor features." (PMID 32591500, 2020). "Moreover, contactin-5 (CNTN5), 26S proteasome non-ATPase regulatory subunit 14 (PSMD14), hepatic and glial cell adhesion molecule (HEPACAM) and hepatocellular Carcinoma, Down-Regulated 1 (HEPN1) are four genes associated with suicidality." (PMID 36979315, 2023).
tumor (3 papers, 2020 to 2024). "In contrast to FN1, downregulation of CNTN5 was shown to be associated with tumor metastasis." (PMID 39770638, 2024). "For both variants, rs78588384 within CNTN5 and rs200077102 within FN1, low MAFs, similar to the MAFs detected in PTC blood and tumor samples, were observed (p ≤ 0.001)." (PMID 39770638, 2024).
neurological disorders (1 paper, 2024). "Even though associations between CNTN5 mutations and neurological disorders have been shown, molecular functions of the molecule are still poorly understood." (PMID 39770638, 2024).
CNTN5 also shares sentences with these, for which no sentence is quoted: schizophrenia (4 papers); bipolar disorder (3); heart failure (2); hyperuricemia (2); neurodevelopmental disorder (2); ovarian carcinoma (2); amyotrophic lateral sclerosis (1); diffuse large B-cell lymphoma (1); eating disorder (1); epilepsy (1); glioma (1); learning disorder (1); lymphoid neoplasm (1); melanoma (1); monocytic leukemia (1); Obesity (1); pancreatic cancer (1); prostate carcinoma (1); psychological distress (1); rheumatoid arthritis (1); Stroke (1).